HMGCS1 (3-hydroxy-3-methylglutaryl-CoA synthase 1)
Diseases named in the same sentence as HMGCS1 in open-access papers (continued):
Sharing a sentence is not in itself a finding about the gene and the disease.
cervical tumor (1 paper, 2020). "miR‐223 was highly expressed in cervical tumor tissues, whereas TGFBR3 or HMGCS1 was significantly downregulated." (PMID 32491253, 2020).
cholestasis (1 paper, 2024). Impairment of the bile flow caused by obstruction within the liver, or outside the liver in the bile duct system. "HMGCS1 was reduced in expression in livers exhibiting cholestasis based upon comparisons of AlbCre and RbpjF/F::AlbCre or Keap1F/F::RbpjF/F::AlbCre mice." (PMID 38731931, 2024). "Probably, the direct NRF2 contributions for enhanced Hmgcs1 expression in cholestasis livers are small, but there might be a KEAP1-dependent signaling effect." (PMID 38731931, 2024).
COVID-19 (1 paper, 2024). A disease caused by infection with severe acute respiratory syndrome coronavirus 2. "Therefore, we explored the common pathogenesis of AMD and SARS-CoV-2, and found that COVID-19 and AMD have five common differences in FAMRG, namely FASD1, HMGCS1, ACOX2, ACAT2 and PECR." (PMID 38625951, 2024).
Cushing syndrome (1 paper, 2022). Cushing's syndrome (CS) encompasses a group of hormonal disorders caused by prolonged and high exposure levels to glucocorticoids that can be of either endogenous (adrenal cortex production) or exogenous (iatrogenic) origin. "KEGG pathway analysis disclosed involvement of HMGCS1 in steroid biosynthesis, Cushing syndrome, cortisol synthesis and secretion, and so forth." (PMID 34549901, 2022).
diabetic foot ulcers (1 paper, 2024). "The upregulation of HMGCS1 and HMGCR leads to increased cholesterol biosynthesis in HUVECs, exacerbating their apoptosis and contributing to the delayed healing of diabetic foot ulcers." (PMID 38811564, 2024). "From our study, we may conclude that the inhibition of the PKCδ-HMGCS1/HMGCR pathway alleviates high glucose-induced endothelial apoptosis and represent a potential therapeutic strategy for diabetic foot ulcers." (PMID 38811564, 2024).
endothelial dysfunction (1 paper, 2025). In vascular diseases, endothelial dysfunction is a systemic pathological state of the endothelium (the inner lining of blood vessels) and can be broadly defined as an imbalance between vasodilating and vasoconstricting substances produced by (or acting on) the endothelium. "This is particularly interesting, as previous studies demonstrated that exosomes from umbilical cord plasma can suppress HMGCS1, thereby inhibiting cholesterol synthesis and ultimately inducing endothelial dysfunction." (PMID 41446579, 2025).
hepatoblastoma (1 paper, 2025). Hepatoblastoma (HB) is a malignant hepatic tumor and is the most common pediatric liver cancer. "Hepatoblastoma exhibited significantly higher levels of cholesterol synthase (SREBF2, SQLE, HMGCS1) compared to normal liver tissues, which indicated higher metabolic activity." (PMID 40271711, 2025).
lentivirus infection (1 paper, 2024). Virus diseases caused by the Lentivirus genus. "AML cell lines overexpressing HMGCS1 THP-1/OE and HL-60/OE were established by lentivirus infection followed by drug selection, and the OE of HMGCS1 was confirmed." (PMID 38994525, 2024).
lymphoma (1 paper, 2021). A malignant (clonal) proliferation of B- lymphocytes or T- lymphocytes which involves the lymph nodes, bone marrow and/or extranodal sites. "However, the mechanism underlying the inhibitory effect of metformin on HMGCS1 in lymphoma cells remains largely unknown." (PMID 34195068, 2021).
melasma (1 paper, 2022). "Furthermore, CTNNB1 was linked to genes like DCT and HMGCS1, which were related to melanin biosynthetic process and lipid metabolic process reported in melasma study." (PMID 34609489, 2022).
non-small cell lung carcinoma (1 paper, 2024). A group of at least three distinct histological types of lung cancer, including non-small cell squamous cell carcinoma, adenocarcinoma, and large cell carcinoma. "Analysis of data from the Cancer Cell Line Encyclopedia (CCLE) revealed that the expression levels of HMGCS1, HMGCR, IDI1, FDFT1, and SQLE were significantly higher in SCLC cell lines compared to non-small cell lung cancer (NSCLC) cell lines and other cancer cell lines." (PMID 39669201, 2024).
osteosarcoma (1 paper, 2023). A usually aggressive malignant bone-forming mesenchymal neoplasm, predominantly affecting adolescents and young adults. "MVP regulation by USP28 was also confirmed in U2OS osteosarcoma cells, where knockout of USP28 reduced expression of HMGCS1 and resulted in a small but significant decrease in cholesterol levels." (PMID 37202505, 2023).
ovarian serous cystadenocarcinoma (1 paper, 2022). A malignant serous cystic epithelial neoplasm arising from the ovary. "However, for other tumors such as LHIC (LGG), ovarian serous cystadenocarcinoma (OV), testicular germ cell tumors (TGCT), and uterine carcinosarcoma (UCS), the expression of HMGCS1 was not significantly different from their controls." (PMID 34549901, 2022).
prostate tumors (1 paper, 2020). "Among these genes, PTEN is an important tumor suppressor gene predominantly involved in human prostate tumors, whereas HMGCS1, HMGCR, SCD1, FABP4, and SCD1are critical enzymes in the pathways of lipid synthesis as well cholesterol and steroid synthesis." (PMID 32180899, 2020). "Consistent with the microarray data, we found a higher expression of HMGCS1 (3.5-fold), HMGCR (2.5-fold), SCD1 (2.5-fold), AGPS (1.9-fold), FABP4 (2.5-fold), DPT (2.2- fold), and PTEN (1.56-fold decline) in prostate tumors of LPB-Tag genotype when compared with the prostates of other genotypes." (PMID 32180899, 2020).
sarcoma (1 paper, 2022). A usually aggressive malignant neoplasm of the soft tissue or bone. "Interestingly, we found that HMGCS1 was obviously over‐expressed in tumor cell lines, especially in hematological malignancies and sarcoma." (PMID 34549901, 2022).
Sepsis (1 paper, 2021). Sepsis is defined as life-threatening organ dysfunction caused by a dysregulated host response to infection. "Hepatic gene expression of the main regulator of the cholesterol pathway, Srebf2, was increased by sepsis whereas hepatic cholesterol-synthesizing enzymes Hmgcs1 and Fdft1 were unaffected, and Aacs expression was decreased compared to healthy mice—all irrespective of 3HB treatment." (PMID 34274000, 2021).
stomach cancer (1 paper, 2020). "Levels of HMGCS1 mRNA in gastric tumor samples from patients were higher than those of adjacent nontumor samples." (PMID 32349352, 2020).
thymic lymphomas (1 paper, 2015).
virus infection (1 paper, 2018). "The mRNA expression of these five genes, HMGCS1, HMGCR, MVD, MVK, and FDPS, was consistently decreased after M1 virus infection in both HCT-116 and SW1990 cell lines." (PMID 29670091, 2018).
cancer (46 papers, 2015 to 2025). A tumor composed of atypical neoplastic, often pleomorphic cells that invade other tissues. "Amplification was the most common genetic alteration of HMGCS1 in different cancers, while the frequency of mutation was low." (PMID 34549901, 2022). "Of particular interest is the elevated expression of circHMGCS1–016, derived from the HMGCS1 gene and locating at chromosome 5p12, a cancer susceptibility region." (PMID 34526098, 2021). "HMGCS1, one of the potential regulatory nodes in the mevalonate pathway, has been implicated in controlling progression and stemness of cancer cells." (PMID 32349352, 2020). "3- hydroxy-3-methylglutaryl-CoA synthase 1 (soluble), HMGCS1 is located on chromosome 5 in which its changes is linked to cancer progression." (PMID 31528309, 2019). "The cellular lysates from H1299 and MDA-MB-231 cancer cells subjected to 24 h serum deprivation exhibited about a two-fold increase in abundance of HMGCS1 and MVD proteins compared with cells cultured with serum." (PMID 41303417, 2025). "It has been reported that Hmgcs1 regulates radiosensitivity of cancer cells by controlling cholesterol metabolism and mitochondrial gene expression." (PMID 39306223, 2025). "The converse also seems to be true, at least in some cancer cells, where HMGCS1 mediates ketogenesis in collaboration with HMG-CoA lyase." (PMID 40305364, 2025). "Animal experiments demonstrate important proof‐of concept in controlling CSN6 or HMGCS1 for HCC treatment such as NAFLD related cancer." (PMID 38308184, 2024). "GEPIA (a web server for cancer and normal gene expression profiling and interactive analyses) was utilized to analyze the clinical influence of HMGCS1 on AML." (PMID 38994525, 2024). "Further developing drug compounds that interfere CSN6‐mediated HMGCS1 stabilization or inhibit HMGCS1 activity by small molecules can be further developed as a rational cancer therapy for CSN6‐overexpressing HCC." (PMID 38308184, 2024). "Recent studies demonstrated that HMGCS1 is a potential metabolic target for the treatment of cancer." (PMID 38263056, 2024). "HMGCS1 was also detected in 103 tissue specimens, and its immunoreactivity was higher in 73 cancer tissues than in 30 normal endometrial tissues (p < 0.001)." (PMID 36835419, 2023). "Recent studies have shown that Hmgcs1 has a potential carcinogenic effect in a wide range of human cancers and is highly expressed in most tumor types, reducing sensitivity to most drugs." (PMID 37828502, 2023). "HMGCS1 expression was negatively correlated with the IF of CD8+ T‐cells in most cancers, such as CESE, HNSC, STAD, and THYM." (PMID 34549901, 2022). "Emerging studies showed that HMGCS1 contributed to the progression of a variety of cancers, including gastric, colon, and cervical cancer." (PMID 34549901, 2022). "The infiltration levels of cancer associated fibroblast and CD8+ T‐cell were closely associated with HMGCS1 expression." (PMID 34549901, 2022). "Mounting evidence has reported a close relationship between HMGCS1 and cancer initiation and progression." (PMID 35242038, 2022). "The statin treatment of cancer cells leads to a compensatory upregulation of HMGCS1, which is widely upregulated in breast and other cancer-types." (PMID 33670680, 2021). "Analyzing cancer genomics datasets showed that the HMGCS1 gene is amplified in various cancers such as stomach, breast, and lung cancers." (PMID 32349352, 2020). "The genes of CTSZ, AFF4, DHRS2, and HMGCS1 known as active agents in cancer progression, were identified as the central DEGs in the constructed PPI network in this study." (PMID 31528309, 2019).
cancer (continued). "From these results, we established CXCR4, CXCL1 and HMGCS1, the intersecting genes of the datasets with high connectivity and p-value of < 0.05, as significant genes in the identification of cancer stem cells." (PMID 26870956, 2016). "Additionally, downregulation of HMGCS1 and Prkcq inhibits cancer cell proliferation, migration, and invasion." (PMID 39796281, 2025). "We hypothesize that ERRα regulates cancer cell membrane structure and function through HMGCS1-mediated intracellular cholesterol metabolism to promote tumor invasion and metastasis." (PMID 36835419, 2023). "In addition, CPTAC dataset was utilized to analyze the HMGCS1 protein level difference among cancers." (PMID 34549901, 2022). "HMGCS1 was highly expressed and negatively correlated with the prognosis in most cancer types." (PMID 34549901, 2022). "Our study revealed the potential oncogenic role of HMGCS1 in cancers." (PMID 34549901, 2022). "The top five genes were HMGCR, LDL1 (low‐density lipoprotein 1), ACAT2 (acetyl‐CoA acetyltransferase 2), NSDHL (NAD[P] dependent steroid dehydrogenase‐like), and LDLR1 (low‐density lipoprotein receptor 1), all of which were positively correlated with HMGCS1 in most cancer types." (PMID 34549901, 2022). "Collectively, we found that the expression of HMGCS1 was correlated with the IF in most cancers." (PMID 34549901, 2022). "HMGCS1 can promote cancer development and affect the function of NK cells." (PMID 33985534, 2021). "Since cholesterol biogenesis may promote the growth of cancer cells, we knocked down HMGCS1 in KLF13 knockdown CRC cells." (PMID 32523679, 2020). "To date, only a few studies have investigated the role of HMGCS1 in cancer development." (PMID 32491253, 2020). "There are few reports about the role of TGFBR3 and HMGCS1, especially HMGCS1 in cancer progression." (PMID 32491253, 2020). "In addition, analysis of cancer genomics datasets using cBioPortal shows that HMGCS1 can be amplified in cancers, including breast and lung." (PMID 26353928, 2015). "In this study, we found that HK2 and HMGCS1 inhibited the elimination of ASSs by binding to P62 to prevent reductions in the lactate and cholesterol concentrations, respectively, and nutrient supplementation provided conditions sufficient for the growth of cancer cells." (PMID 40097416, 2025). "Moreover, in agreement with the MVA pathway being regulated by the EWSR1-FLI1/EGR2 axis, the global expression of 16 MVA pathway enzymes, and specifically the 2 rate-limiting genes HMGCR and HMGCS1, was significantly higher in Ewing cell lines as compared with other cancer cell lines." (PMID 35565457, 2022). "Blocking the expansion of BCSCs through inhibition of the HMGCS1 gene could be a more efficient approach to control the over-production of isoprenoids compared to standard doses of statins, thereby reducing the proliferation of progenitor cells and cancer development." (PMID 38254664, 2024). "Using various orthotopic mice cancer models, we uncovered that MVA pathway regulator HMGCS1 was essential to promote tumor progression and YAP activation in HCC." (PMID 38308184, 2024). "In human cancer cells, PPAR-α, a key transcriptional regulator of lipid metabolism, cross-talks with SREBP to regulate the expression of Hmgcs1 and Msmo1." (PMID 39062636, 2024). "Further, HMGCS1 can induce transcriptional upregulation of pluripotency genes POU5F1 (Oct4) and SOX2 and is a key mediator of cancer stem cell enrichment in breast cancer." (PMID 37958351, 2023). "Next, we analyzed the HMGCS1 expression of normal and tumor tissues from GSCA approach across different cancer types in TCGA." (PMID 34549901, 2022). "Our study indicates upregulation of multiple genes that are particularly enzymes involved in cholesterol biosynthesis, i.e., GGPS1, SQLE, FDPS, HMGCS1, and HMGCR, which were also reported in distinct cancer models." (PMID 35050168, 2022).
cancer (continued). "Camptothecin amplified the effects seen in cancer (CHECK2, BCL-2 and IL8), but opposed them for CYP51A1, ITGA2, DHCR7 or HMGCS1." (PMID 28962550, 2017). "Apparently, HMG-CoA lyase is not exclusively a mitochondrial enzyme; in some cancer cells, HMGCS1 and HMG-CoA lyase colocalize and together they generate acetoacetate in the cytoplasm." (PMID 40305364, 2025). "Hypoxia in the tumor micro‐environment leads to up‐regulation of lipid metabolism‐related genes, such as ACSS2, which enhances lipid metabolism reprogramming through pathways like HMGCS1 mediated PI3K/AKT/mTOR, promoting the progression of various cancers, including pNETs." (PMID 39524139, 2024). "Emerging studies reveals that 3‐hydroxy‐3‐methylglutaryl‐CoA synthase 1 (HMGCS1) plays vital oncogenic roles in a broad spectrum of human cancers, but there is no pan‐cancer evidence on the relationship between HMGCS1 and various tumor types." (PMID 34549901, 2022). "The role and regulatory mechanism of HMGCS1 in cancer development and progression are complicated and not yet fully understood." (PMID 32349352, 2020). "Some of these treatments could oppose the deregulations occurring in cancer samples, including those of the CHECK2, CYP51A1, HMGCS1, ITGA2, NME1 or VEGFA genes." (PMID 28962550, 2017). "In addition, the increased expression of MSMO1, HMGCS1, MVD, and SREBF2 across solid tumors vs. normal tissues based on the analysis of TCGA datasets further signifies the crucial role of these metabolic genes in multiple cancers." (PMID 37745085, 2023). "However, there is no pan‐cancer evidence on the relationship between HMGCS1 and various tumor types based on big clinical data." (PMID 34549901, 2022). "Decreased expression of both isomiR and canonical miRNA during cancer progression (from non-cancer parental cell line to invasive cancer) was observed; indeed, miR-140-3p-1 acted as a tumor suppressor, with loss of miR-140-3p-1 promoting upregulation of HMGCR and HMGCS1." (PMID 34573429, 2021). "Our previous study has proved that HMGCS1 promoted cell growth in leukemia (data not shown) and BRAFV600E‐positive human cancers." (PMID 34549901, 2022). "Glycosylation of HMGCS1 and AOC3 proteins have not been reported in any cancer types." (PMID 35752862, 2022).